MIR141 (microRNA 141)
Synonyms: hsa-mir-141; MIRN141; mir-141
Gene: MicroRNA gene on chromosome 12 (6,964,097 to 6,964,191, forward strand). Ensembl gene ENSG00000207708.
Gene Ontology:
Biological process: miRNA-mediated post-transcriptional gene silencing
Cellular component: RISC complex
Diseases named in the same sentence as MIR141 in open-access papers:
MIR141 is named in the same sentence as 8 diseases in open-access papers, as found by Europe PMC text mining. Sharing a sentence is not in itself a finding about the gene and the disease. The quoted sentences say what the papers report.
follicular thyroid carcinoma (1 paper, 2012). "An investigation into the expression of MIR141 in a series of archival thyroid malignancies [n = 140; classic PTC (cPTC), follicular variant PTC, follicular thyroid carcinoma, Hashimoto thyroiditis (HT), or control thyrocytes] was performed." (PMID 22969748, 2012).
cancer (2 papers, 2015 to 2020). A tumor composed of atypical neoplastic, often pleomorphic cells that invade other tissues. "The differentially regulated miRNAs include Mir1-1, Mir125b-2 and Mir141, which have well-known roles in cancer development." (PMID 26461935, 2015). "GRHL2 upregulates expression of the MIR141, MIR200A, MIR200B, MIR200C and MIR429 microRNAs by binding to their regulatory elements in a number of cancers." (PMID 32005677, 2020).
tumor (1 paper, 2018). "To distinguish the specific roles of the miR-200c and miR-141 families, we infected RT2_DKO tumor-derived cells with adenoviruses harboring either the endogenous Mir141~200c locus (ad-141~200c) or the Mir141 or Mir200c genes alone (ad-141 and ad-200c, respectively)." (PMID 30405106, 2018).
MIR141 also shares sentences with these, for which no sentence is quoted: goiter (1 paper); Hashimoto thyroiditis (1); infection (1); papillary thyroid cancer (1); thyroid (1).